CRP (C-reactive protein)
Diseases named in the same sentence as CRP in open-access papers (continued):
Sharing a sentence is not in itself a finding about the gene and the disease.
lung cancer (continued). "Related to this, it was very recently reported that CRP and IL-6 levels were significantly higher among 10,061 atherosclerosis patients subsequently diagnosed with lung cancer than among those not subsequently diagnosed with lung cancer." (PMID 33173057, 2020). "In addition, a prognostic value of CRP – as part of a score and alone - in patients receiving ICI therapy was suggested for lung cancer patients before." (PMID 32238865, 2020). "The c-reactive protein (CRP), carbohydrate antigen 19-9 (CA19-9), carbohydrate antigen 15-3 (CA15-3), carcinoembryonic antigen (CEA), and cancer antigen 125 (CA125) are the majority of tumor markers used for the detection of lung cancers." (PMID 33143045, 2020). "Despite that, proteomic studies continue to provide evidence that acute phase proteins, like CRP and AAT, could be useful biomarkers in early detection of lung cancer and in monitoring its evolution." (PMID 31487965, 2019). "It should be born in mind that PTX-3 levels are statistically significantly increased in patients with lung cancer and/or aged over 65 years, and the correlation between the PTX-3, CRP, and WBC levels in patients who underwent posterolateral thoracotomy was insignificant." (PMID 31086534, 2019). "The CRP/ALB ratio was also applied to predicting the prognosis of patients with cancer and its usefulness has been reported in patients with various cancers, such as hepatocellular carcinoma, esophageal cancer and lung cancer." (PMID 27812440, 2016). "Gel bands show a mass of 12–14 kDa, indicating CRP complexes, in the serum samples from lung cancer patients but not in healthy control samples." (PMID 26264146, 2015). "We detected the existence of CRP-SAA in the mixed serum sample from 10 lung cancer patients on which we previously performed the proteomics analysis and some serum samples from individual lung cancer patients by co-IP." (PMID 26264146, 2015). "Also in a study of lung cancer, patients with cachexia had heightened inflammatory responses manifested as increases of serum IL-6, soluble TNF-α receptor and C-reactive protein (CRP)." (PMID 25010770, 2014). "The proteins related to host defense, CRP, C9 and SERPINA3, are elevated in lung cancer and may arise from tumor-induced stromal inflammation." (PMID 25114662, 2014). "Additionally, the predictive accuracy of certain composite nutritional inflammatory indices, such as the Advanced Lung Cancer Inflammation Index (ALI), compared to single indicators, C-reactive protein (CRP), remains unclear." (PMID 39726875, 2024). "In blood tests, the lung cancer group showed no change in the total white blood cell count, but the neutrophil percentage decreased, the lymphocyte percentage increased, the N/L ratio decreased, and the CRP level decreased mildly." (PMID 38143707, 2023). "The analysis also reported that baseline concentrations of CRP (6.0 mg/L vs. 4.2 mg/L; p < 0.0001) and IL-6 (3.2 vs. 2.6 ng/L; p < 0.0001) were significantly higher among participants subsequently diagnosed with lung cancer than among those not diagnosed with cancer." (PMID 35872912, 2022). "In our study, CRP levels and TNF-α levels were significantly decreased, suggesting that ω-3 PUFAs may have some regulatory effect on the inflammatory status in patients treated with lung cancer radiotherapy and chemotherapy." (PMID 35910071, 2022). "Non-lung cancer mortality was considerably high (>30% at five years) in the inoperable patients, which might have diminished the negative effect of CRP on survival." (PMID 34350956, 2021). "There was no significant impact of CRP or SMM on lung cancer death or non-lung cancer death." (PMID 34350956, 2021). "However, CRP elevation could not be attributed to cancer in the present study because patients with lung cancer may also have inflammation such as cancer-related lung infection." (PMID 38750432, 2024).
lung cancer (continued). "In addition, serum levels of pro-CRP, NSE, and CAE in patients with benign lung tumors were 28.9 pg/mL, 12.5 ng/mL, and 10.8 ng/mL, respectively, which were lower than 175.6 pg/mL, 33.6 ng/mL, and 31.9 ng/mL in patients with malignant lung tumors significantly (P < 0.05)." (PMID 35572829, 2022). "However such comparison is not adequate for attributing raised CRP to cancer, as lung cancer patients may have concomitant inflammation from other sources such as cancer-related pulmonary infection." (PMID 26678281, 2016). "The significance of IL-17A, CRP and IL-6 suggests that not just Th-2 or Th-17 cells are important in lung cancer progression and supports our hypothesis that the inclusion of a broader cytokine panel can capture the multi-faceted role of inflammation in lung cancer." (PMID 28402963, 2017). "Intraoperative ECMO for lung cancer resections did not impact CTC variation after the procedure and did not impact postoperative complications, ICU stay, hospital total length of stay, and post operative C-reactive protein increase." (PMID 36291788, 2022). "Our contrasting findings may be related to the presence or absence of lung cancer, though the use of different biomarkers -NLR vs CRP - is also likely a critical parameter." (PMID 36544783, 2022). "We speculated P6 was noninfectious, which agreed with the clinical diagnosis (lung cancer) and the levels of serological infection markers procalcitonin (PCT) and C-reactive protein (CRP)." (PMID 29988504, 2018).
atrial fibrillation (288 papers, 2008 to 2026). A disorder characterized by an electrocardiographic finding of a supraventricular arrhythmia characterized by the replacement of consistent P waves by rapid oscillations or fibrillatory waves that vary in size, shape and timing and are accompanied by an irregular ventricular response. "Multivariable analysis identified higher admission NIHSS score, fasting plasma glucose, hs-CRP, D-dimer, atrial fibrillation history, and large infarction as independent risk factors for END." (PMID 42256574, 2026). "Various inflammatory markers, including C-reactive protein, tumor necrosis factor-α, and interleukins 2, 6, and 8, have been linked to atrial fibrillation." (PMID 39105025, 2024). "Prospective studies in some Western countries have shown that increased expression of serum high-sensitivity CRP can be used as a marker of systemic inflammation and as a risk factor for the development of atrial fibrillation." (PMID 38750504, 2024). "In multivariate analyses, PTX-3 was negatively associated with BMI while it was positively associated with atrial fibrillation, sST2 levels, and C-reactive protein." (PMID 38397422, 2024). "High-sensitivity CRP level is believed to be associated with both the maintenance and recurrence of atrial fibrillation." (PMID 38750504, 2024). "Inflammatory markers such as c-reactive protein (CRP) and interleukin-6 have been associated with an increased risk of atrial fibrillation and have been linked to chronic atrial fibrillation, left atrial dilation, and the promotion of a pro-thrombotic state." (PMID 37568436, 2023). "CRP as an inflammatory marker has been associated with atrial fibrillation, including development, recurrence, and total burden, as well as associated with thromboembolic complications." (PMID 37360331, 2023). "Patients with higher levels of CRP in the plasma have more atrial fibrillation episodes, and baseline plasma CRP levels are predictive of the future risk of atrial fibrillation." (PMID 37089888, 2023). "A meta-analysis based onlarge-scale data found that high-sensitivity C-reactive protein and interleukin-6were strongly associated with atrial fibrillation recurrence." (PMID 39076272, 2023). "Despite the known association between atrial fibrillation and elevated CRP levels, the inflammation marker has independently impacted outcomes." (PMID 37360331, 2023). "In a set of more than 600 patients, we show that mid-term clinical outcomes and mortality are significantly and independently associated with initial CRP levels, particularly in patients suffering from atrial fibrillation." (PMID 37360331, 2023). "This fits the known association of CRP levels in atrial fibrillation with burden and severity of thromboembolic events." (PMID 37360331, 2023). "High CRP level is not only associated with the presence and future development of atrial fibrillation, but also predictive of atrial fibrillation after surgery." (PMID 35707008, 2022). "A recent study showed that Hs-CRP levels were independently associated with END in cerebral embolism caused by atrial fibrillation (AF)." (PMID 35711907, 2022). "With increased inflammation, as defined by serum levels of CRP, C3 and C4, the risk of atrial fibrillation increase." (PMID 33407078, 2021). "Following the event of myocardial ischemia, local as well as systemic inflammation arises, which causes the release of various inflammatory factors such as IL-6 and CRP, which have been independently associated with the development of atrial fibrillation." (PMID 35008432, 2021). "7,8 Moreover, high levels of C-reactive protein, which is associated with atrial fibrillation, can be seen in vitamin D deficiency." (PMID 34326963, 2021). "Hs-CRP was an independent risk factor for post-CABG atrial fibrillation (POAF) (OR = 1.212, P = 0.01)." (PMID 34332541, 2021).
atrial fibrillation (continued). "Adjusting for age, BMI and statin use, high CRP levels were additionally associated with atrial fibrillation, right ventricular dysfunction, and higher N-terminal pro-B-type natriuretic peptide levels (P<0.05 for all)." (PMID 30114262, 2018). "In human patients, C-reactive protein has been associated with incidence of atrial fibrillation and was able to predict future development and polymorphisms in the interleukin-1 family affect risk for atrial fibrillation." (PMID 30534081, 2018). "A Mendelian randomization of 47,000 individuals from the general population Does elevated C-reactive protein increase atrial fibrillation risk?" (PMID 27699086, 2016). "Mendelian randomisation has shown that an elevation of CRP is rather an effect than a cause of atrial fibrillation." (PMID 25037974, 2014). "Inflammation, determined by elevations in C-reactive protein and related biomarkers, has been associated with the presence of atrial fibrillation and future development of atrial fibrillation." (PMID 25119880, 2014). "Atrial fibrillation is associated with elevated levels of C-reactive protein (CRP), interleukin (IL-2, IL-6, and IL-8) and other inflammatory markers (tumour necrosis factor alpha; TNF-α) that may increase oxidative stress and endothelial injury." (PMID 39200396, 2024). "Moreover, increased C-reactive protein (an inflammatory biomarker) levels have been linked to atrial fibrillation development, recurrence, perpetuation, and thromboembolic complications." (PMID 37856566, 2023). "C-reactive protein and microalbuminuria are associated with atrial fibrillation." (PMID 35946695, 2022). "In men on antihypertensive treatment those with hyperuricemia (> 410 μmol/L) had the most adverse biological risk profile for HF including the highest rates of atrial fibrillation and renal dysfunction and the highest mean level of BMI, c-reactive protein and cardiac function (cardiac troponin T)." (PMID 29208425, 2018). "Interestingly, levels of miRNA-146b-5p and miRNA-155, which are known to be associated with inflammation, were independently and positively associated with left atrium dimension, atrial fibrillation duration and high sensitivity C-reactive protein levels." (PMID 26319023, 2015). "The rationale of the clinical trial was based on the association between atrial fibrillation (AF) and inflammation and evidence supporting increased CRP levels as a risk for AF development and perpetuation." (PMID 30090066, 2018). "In an analysis of 478,524 individuals from the UK Biobank cohort, C-reactive protein (CRP) levels were found to be significantly and positively associated with the risk of developing atrial fibrillation." (PMID 40873621, 2025). "Significant differences were observed for pre-operative CRP, postoperative atrial fibrillation, and intubation time, which increased progressively with OSA severity (p < 0.05)." (PMID 41153825, 2025). "Compared with AS group, CE group had older age, higher pre-thrombolytic NIHSS score, lower systolic blood pressure, fewer platelets, higher urea, higher CRP, and a greater proportion of patients with a history of atrial fibrillation (P < 0.05)." (PMID 39987236, 2025). "Studies have shown that C-reactive protein is an independent risk factor for atrial fibrillation, and OSA can increase C-reactive protein levels." (PMID 40166062, 2025). "In a cohort of 2434 women, a significant relation between inflammatory markers such as CRP, fibrinogen, and soluble intercellular adhesion molecule-1 and new onset atrial fibrillation at a median follow-up of 14.4 years was proven." (PMID 38672728, 2024). "The iSAP group had higher rates of risk factors like older age, atrial fibrillation, COPD, and ESS, along with elevated levels of WBC, CRP,and FT4 levels (all P < 0.001)." (PMID 39588332, 2024).
atrial fibrillation (continued). "More uptake of PHE by the heart [from the aortic root to the coronary sinus, Δ(AO-CS)] was associated with higher creatinine, uric acid, and PHE (AO) and the presence of atrial fibrillation, but lower CRP." (PMID 39064291, 2024). "Relevant non echocardiographic clinical predictors of poor outcome after TAVI include atrial fibrillation and elevated CRP levels." (PMID 38252146, 2024). "In our investigation, we observed a significant positive correlation between the levels of SIRI and CRP in patients diagnosed with atrial fibrillation." (PMID 37507722, 2023). "Moving from cluster 1 to cluster 3, we found an increase in the prevalence of atrial fibrillation and concurrent bacterial infection, as well as an increase in NT-proBNP and CRP levels, together with a decrease in eGFR levels." (PMID 37760914, 2023). "Patients with reduced LVEF were more likely to present with shortness of breath; had a higher proportion of atrial fibrillation/flutter rhythm; and had higher levels of creatinine, hs-cTnI, C-reactive protein, and D-dimer but lower nadir levels of albumin." (PMID 38137638, 2023). "CRP levels were highly predictive for impaired outcomes, especially in patients with atrial fibrillation, in both univariate and multivariate models." (PMID 37360331, 2023). "Patients in cluster 3 were older and had a higher prevalence of atrial fibrillation, higher admission NT-proBNP and C-reactive protein levels, higher prevalence of concurrent bacterial infections, and lower estimated glomerular filtration rates." (PMID 37760914, 2023). "In a moderation analysis, it was shown that the importance of CRP levels for clinical outcomes is predominantly seen in patients with atrial fibrillation." (PMID 37360331, 2023). "HT was associated with a significantly higher incidence of atrial fibrillation, NIHSS score, diastolic blood pressure at admission, international normalized ratio, D-dimer level, and C-reactive protein level (p < 0.05)." (PMID 36875705, 2023). "The conditional effect of initial CRP levels on poor outcomes remained significant for the atrial fibrillation group (p < 0.001)." (PMID 37360331, 2023). "In another meta-analysis in the literature, high CRP levelswere reported to be a predictor of postoperative atrial fibrillation in patientsundergoing coronary artery surgery." (PMID 37403893, 2023). "Score 5 additionally included the GRSs for atrial fibrillation, BMI, C-reactive protein, DBP, PP, heart rate response to exercise, LDL cholesterol, HDL cholesterol, triglycerides, HF, imaging traits, and resting Tpe." (PMID 35861959, 2022). "In multivariate analysis, we found positive associations between admission level of periostin and atrial fibrillation, admission white blood cell (WBC) count, neutrophile–lymphocyte ratio (NLR), creatinine, C-reactive protein (CRP), and glucose level." (PMID 36010292, 2022). "Studies have shown that EAT volume correlates with serum c-reactive protein (CRP) in those with recurrent atrial fibrillation suggesting inflammation as the mediator between EAT and the risk of cardiac arrhythmias." (PMID 36505155, 2022). "Tachycardia and atrial fibrillation were identified, with elevated D-dimer, N-terminal pro-B-type natriuretic peptide, creatine kinase, and C-reactive protein levels." (PMID 36317095, 2022). "The high D-dimer group had less atrial fibrillation, more distant metastasis, lower mean hemoglobin level, lower mean platelet count, prolonged prothrombin time, and higher mean C-reactive protein levels than the low D-dimer group." (PMID 35401408, 2022). "Only prothrombin and CRP were correlated only together, and lactate was correlated with O2 saturation < 88, yno2 and atrial fibrillation." (PMID 34496940, 2021). "Atrial fibrillation, high level of hypersensitive C-reactive protein, high level of uric acid, high NIHSS score before thrombolysis, and high systolic pressure 2 h after thrombolysis (especially more than 150 mmHg) also increased the risk of HT." (PMID 33224083, 2020).